UNC13D (unc-13 homolog D)
Description:
Plays a role in cytotoxic granule exocytosis in lymphocytes. Required for both granule maturation and granule docking and priming at the immunologic synapse. Regulates assembly of recycling and late endosomal structures, leading to the formation of an endosomal exocytic compartment that fuses with perforin-containing granules at the immunologic synapse and licences them for exocytosis. Regulates Ca(2+)- dependent secretory lysosome exocytosis in mast cells.
Synonyms: Munc13-4; HLH3; HPLH3
Tractability: Antibody: its Gene Ontology location is reachable by antibodies, with high confidence; UniProt places it where antibodies can reach, with medium confidence. PROTAC: ubiquitination databases record sites on it; its protein half-life has been measured.
Gene: Protein-coding gene on chromosome 17 (75,827,225 to 75,845,353, reverse strand). Ensembl gene ENSG00000092929.
Subcellular location: Cytoplasm; Membrane; Late endosome; Recycling endosome; Lysosome
Subcellular location (Human Protein Atlas): Cytosol; Vesicles
Pathways (Reactome):
Immune System: Neutrophil degranulation
Gene Ontology:
Molecular function: protein binding; small GTPase binding
Biological process: positive regulation of exocytosis; positive regulation of regulated secretory pathway; regulation of mast cell degranulation; secretion; platelet dense granule organization; positive regulation of substrate adhesion-dependent cell spreading; vasculature development
Cellular component: cytosol; exocytic vesicle; lysosome; Weibel-Palade body; azurophil granule lumen; extracellular region; cytoplasm; late endosome; membrane; recycling endosome
Genetic constraint (gnomAD): Loss-of-function variants: 116 observed, 146.56 expected, observed/expected ratio (o/e) 0.79, 90% interval 0.68 to 0.92. The upper end of that interval is the gene's LOEUF score, 0.92, which puts it in group 3 of 6, group 1 being the genes least tolerant of losing a copy. Missense variants: 1,369 observed, 1,414.5 expected, observed/expected ratio (o/e) 0.97, 90% interval 0.93 to 1.01. Synonymous variants: 588 observed, 594 expected, observed/expected ratio (o/e) 0.99, 90% interval 0.92 to 1.06.
Gene-disease validity (ClinGen):
ClinGen rates the evidence that UNC13D causes each of these diseases.
familial hemophagocytic lymphohistiocytosis 3 (autosomal recessive): Definitive.
Homologues: Orthologues: chimpanzee UNC13D (99% identical), macaque UNC13D (98% identical), dog UNC13D (90% identical), pig UNC13D (90% identical), mouse Unc13d (88% identical), rat Unc13d (88% identical), guinea pig UNC13D (87% identical), tropical clawed frog unc13d (59% identical), zebrafish unc13d (44% identical), Caenorhabditis elegans aex-1 (17% identical). Paralogues in human: BAIAP3 (34% identical).
Diseases named in the same sentence as UNC13D in open-access papers:
UNC13D is named in the same sentence as 61 diseases in open-access papers, as found by Europe PMC text mining. Sharing a sentence is not in itself a finding about the gene and the disease. The quoted sentences say what the papers report.
hemophagocytic lymphohistiocytosis (18 papers, 2014 to 2025). "After conducting a literature review spanning nearly seven years, we identified 18 adult patients diagnosed with hemophagocytic syndrome who exhibited mutations in the UNC13D gene." (PMID 41394838, 2025). "Mutations on UNC13D lead to defects in the cell destruction process, which cause a severe inflammatory syndrome called hemophagocytic lymphohistiocytosis." (PMID 35207686, 2022). "The remaining patient was tested via multigene panel for familial hemophagocytic lymphohistiocytosis, which revealed this variant: UNC13D (NM_199242.3): c.3049G > A, p.Glu1017Lys, homozygous, classified as likely pathogenic." (PMID 34537050, 2021). "UNC13D, which encodes the Munc13–4 protein, is a critical gene implicated in type 3 familial hemophagocytic lymphohistiocytosis (HLH)." (PMID 40943599, 2025). "Others include known genetic causes of hemophagocytic lymphohistiocytosis (HLH) such as defects in the genes PRF1, UNC13D, STX11, STXBP2, LYST, and RAB27A." (PMID 38624552, 2020). "The synergistic defect of AP3B1 with UNC13D can lead to hemophagocytic lymphohistiocytosis." (PMID 38886689, 2024). "Primary HLH, also termed familial hemophagocytic lymphohistiocytosis (FHL), is an autosomal recessive genetic disorder with five major causative genes, namely, HPLH1, PRF1, UNC13D, STX11 and STXBP2." (PMID 29783935, 2018).
Familial hemophagocytic lymphohistiocytosis (12 papers, 2013 to 2025). Familial Hemophagocytic lymphohistiocytosis (FHL) is a rare primary immunodeficiency characterized by a macrophage activation syndrome (see this term) with an onset usually occurring within a few months or less common several years after birth. "UNC13D deficiency is the most common form of familial hemophagocytic lymphohistiocytosis (FHL) in Asia." (PMID 40901478, 2025). "This study aims to discuss the clinical manifestations and treatment of Familial hemophagocytic lymphohistiocytosis (FHL) caused by a mutation in the UNC13D gene." (PMID 38887297, 2024). "Recently, UNC13D, which is associated with familial hemophagocytic lymphohistiocytosis (FHL3), was reported to colocalize and directly interact with STING and inhibit STING oligomerization." (PMID 39478149, 2024). "A targeted genetic testing strategy has also been described for screening newborns for familial hemophagocytic lymphohistiocytosis (FHLH) due to UNC13D inversion mutations." (PMID 29116556, 2018). "The frequency of mutations in HLH-related genes varies by country, with PRF1 and UNC13D mutations accounting for approximately 55% and 32% of Familial hemophagocytic lymphohistiocytosis (FHL) in Japan, respectively, while UNC13D mutations account for the majority of FHL in Korea." (PMID 34344437, 2021). "This approach has also been described as a potential method by which infants with familial hemophagocytic lymphohistiocytosis (FHLH) due to mutations in UNC13D may be identified." (PMID 29116556, 2018). "Germline mutations in genes involved in perforin-granzyme-mediated cytotoxicity such as PRF1, UNC13D, STX11, and STXBP2 were known to cause familial hemophagocytic lymphohistiocytosis (FHL)." (PMID 38404589, 2024). "Bi-allelic null mutations affecting UNC13D, STXBP2, or STX11 result in defects of lymphocyte cytotoxic degranulation and commonly cause familial hemophagocytic lymphohistiocytosis (FHL) in early life." (PMID 28848550, 2017). "Specifically, most patients clustered within the immune dysregulation category were diagnosed with familial hemophagocytic lymphohistiocytosis (FHL) type 2 (n=3/10;30%), type 3 (n=2/10; 20%) and type 4 (n=1/10; 10%), based on homozygotic pathogenic variants in PRF1, UNC13D, and STX11, respectively." (PMID 34992599, 2021). "Germline mutations in genes involved in perforin-granzyme-mediated cytotoxicity such as PRF1, UNC13D, STX11, and STXBP2 were known to induce familial HLH (FHL)." (PMID 38404589, 2024).
macrophage activation syndrome (9 papers, 2012 to 2025). A complication of rheumatic disease that is caused by excessive activation and uncontrolled proliferation of T lymphocytes and well-differentiated macrophages. "A heterozygous mutation occurring in a specific UNC13D intronic region has been regarded as responsible for development of sJIA and recurrent macrophage activation syndrome (MAS), probably due to an impaired lymphocyte-specific downregulation of the NF-kB." (PMID 36768167, 2023). "A previous study also reported genetic association between the MUNC13-4 (UNC13D) sequence polymorphisms and sJIA/macrophage activation syndrome (MAS)." (PMID 33076506, 2020). "However, in recurrent macrophage activation syndrome (MAS) and systemic juvenile idiopathic arthritis patients, c.117 + 143A>G mutation did not affect UNC13D expression in other immune cell types." (PMID 39469717, 2024).
Griscelli syndrome type 2 (6 papers, 2012 to 2025). Griscelli syndrome type 2 (GS2) is a rare, inherited condition that affects the skin, hair, and immune system. "Patients were divided into four groups: 1) with PRF1 mutation (n = 46), 2) with UNC13D mutation (n = 38), 3) with STX11/STXBP2 mutation (n = 25) and 4) with Griscelli syndrome type 2/ Chediak–Higashi syndrome (GS2/CHS) diagnosis (n = 44)." (PMID 40263637, 2025). "The following FHL subtypes have been described: FHL-2 due to mutations in PRF1, FHL-3 (UNC13D), FHL-4 (STX11), FHL-5 (STXBP2), Griscelli Syndrome type 2 (RAB27A) and Chediack-Higashi syndrome (LYST)." (PMID 37426667, 2023).
autoimmune disease (4 papers, 2013 to 2025). A disorder resulting from loss of function or tissue destruction of an organ or multiple organs, arising from humoral or cellular immune responses of the individual to their own tissue constituents. "UNC13D variations were reported in autoimmune disorders like systemic juvenile idiopathic arthritis." (PMID 39992598, 2025). "While primary HLH typically manifests in children due to mutations in genes such as PRF1, UNC13D, STX11 and STXBP2, secondary HLH is more common in adults and is usually triggered by infections, cancers, autoimmune disorders or immunosuppressive therapy." (PMID 41181728, 2025). "To assess the variation frequency in the general populations and in subjects with a different autoimmune disease, we sequenced UNC13D in 61 healthy controls and 38 patients with MS." (PMID 23840885, 2013). "However, a possible role of UNC13D in development of autoimmune diseases other than ALPS has been previously suggested in patients with SJIA, who may also display decreased NK function." (PMID 23840885, 2013).
lymphoma (4 papers, 2023 to 2025). A malignant (clonal) proliferation of B- lymphocytes or T- lymphocytes which involves the lymph nodes, bone marrow and/or extranodal sites. "The prognosis of patients with HLH and heterozygous UNC13D mutations should be correlated with the age of onset; many subsequent developments can lead to lymphoma." (PMID 41394838, 2025). "Several reports of lymphoma in patients with hypomorphic cytotoxicity defects, e.g. in PRF1 or UNC13D, imply a predisposition to lymphoma." (PMID 37388727, 2023). "Although larger cohort studies and functional assays are essential to clarify the contribution of this variant to disease pathogenesis, multiple previous studies have verified that haploinsufficiency of UNC13D increased the risk for lymphoma or extreme high hyperinflammatory status after infection." (PMID 40943599, 2025). "The allele frequency of UNC13D c.2588G>A in lymphoma patients was significantly higher compared with that in the healthy controls (10% versus 1.9%), suggesting that haploinsufficiency of this gene may predispose patients to lymphomas." (PMID 38404589, 2024). "In this study, we reported a unique group of 3 patients with germline mutations of UNC13D and STX11 genes and presented as adult-onset peripheral T-cell lymphoma (PTCL) with cytotoxic T-cell phenotype and atypical lymphoma presentations." (PMID 38404589, 2024). "Moreover, we reviewed the existing literature on UNC13D c.2588G>A and found that this variant was frequently associated with a number of diseases, including HLH, lymphomas, MAS, and ALPS." (PMID 40943599, 2025). "Data showed that the heterozygous variant of UNC13D c.2588G>A might act as a genetic risk factor predisposing carriers to diseases like HLH, lymphoma, etc." (PMID 40943599, 2025).
Pancytopenia (4 papers, 2017 to 2026). An abnormal reduction in numbers of all blood cell types (red blood cells, white blood cells, and platelets). "Since patients with UNC13D deficiency frequently present with significantly reduced leukocyte counts (pancytopenia), UNC13D expression can instead be analyzed on platelets (CD41a+), since platelets express UNC13D more abundantly than peripheral blood leukocytes." (PMID 31849949, 2019). "Specifically, this was the case for a TCIRG1 variant in a patient with pancytopenia, an IL36RN variant in a patient with refractory eczema, and in a UNC13D variant in a patient with hemophagocytic lymphiohistiocytosis." (PMID 34992599, 2021).
viral infection (4 papers, 2017 to 2025). "For example, viral infection may alter the intracellular environment, triggering the production of cytokines and signaling molecules that interfere with the normal expression and regulation of UNC13D, thereby accelerating the emergence of disease-causing mutations." (PMID 41394838, 2025). "We hypothesize that if the onset of mutation occurs in UNC13D, this will further disrupt the balance of the immune system, increase the likelihood of related diseases, or aggravate the existing condition due to further disorders of the immune system after viral infection." (PMID 41394838, 2025).
COVID-19 (3 papers, 2021 to 2025). A disease caused by infection with severe acute respiratory syndrome coronavirus 2. "The total percentage of COVID-19 patients with variants in UNC13D or AP3B1, two typical HLH genes, was dramatically higher in high-level cytokine group than in low-level group (33.3 vs. 5.7%, P < 0.001)." (PMID 33867526, 2021). "Mutations in UNC13D have been associated with severe cytokine storms in patients with COVID-19, which may result in impaired immunological responses, thereby aggravating inflammation and increasing the risk of cardiovascular incidents during COVID-19 infection." (PMID 40002898, 2025). "The results of these genetic factors in the genes (TLR7, UNC13D, DES, SPEG, LZTFL1, ABO, ILRUN, and CACFD1) provide substantial insights into the genesis of cardiovascular issues linked with COVID-19." (PMID 40002898, 2025). "Studies have shown that mutations in genes related to the immunological response, including Toll-Like Receptor 7 (TLR7) and Unc-13 Homolog D (UNC13D), correlate with adverse COVID-19 consequences." (PMID 40002898, 2025). "Germline variants in UNC13D and AP3B1 were associated with the development of severe cytokine storms, fatal outcomes in COVID-19." (PMID 33867526, 2021). "We conducted whole-exome sequencing in 233 hospitalized COVID-19 patients and identified four PID gene (UNC13D, AP3B1, RNF168, DHX58) variants were significantly enriched in COVID-19 patients experiencing severe cytokine storms." (PMID 33867526, 2021).
Primary hemophagocytic lymphohistiocytosis (3 papers, 2022 to 2026). "Rare heterozygous missense variants in genes responsible for primary hemophagocytic lymphohistiocytosis (LYST, STXBP2, PRF1, UNC13D, AP3B1, and DOCK8) were found in patients with MIS-C." (PMID 38397896, 2024). "Thirty-nine children were diagnosed with MIS-C, and 25.4% of the 39 MIS-C patients harbored rare heterozygous missense mutations either in primary hemophagocytic lymphohistiocytosis (pHLH) genes (LYST, STXBP2, PRF1, UNC13D, AP3B1) or the HLH-associated gene DOCK8 (four variants)." (PMID 35336791, 2022).
systemic juvenile idiopathic arthritis (3 papers, 2008 to 2025). "In the present study we therefore hypothesized that defective apoptosis in patients with systemic-onset JIA could be due to polymorphisms in the genes PRF1, GZMB, UNC13D, or Rab27a." (PMID 18311812, 2008).
albinism (2 papers, 2015). A congenital disorder characterized by partial or complete absence of melanin pigment in the eyes, hair, or skin. "Interestingly, one such patient with albinism (P1) was diagnosed with a homozygous UNC13D splice-site mutation (c.570-1G>A)." (PMID 26684649, 2015).
asthma (2 papers, 2024 to 2026). "Five druggable genes significantly associated with asthma were identified in whole blood (IRF1, OXER1, PSMA4, UNC13D, and HLA‐DRB1) and one in lung tissue (CD226)." (PMID 41573111, 2026). "IRF1 (PPH4/PPH3 + PPH4 = 0.975), OXER1(PPH4/PPH3 + PPH4 = 0.967), PSMA4(PPH4/PPH3 + PPH4 = 0.972), UNC13D (PPH4/PPH3 + PPH4 = 0.989) and HLA‐DRB1(PPH4/PPH3 + PPH4 = 0.948) expression had significant colocalization associations with asthma." (PMID 41573111, 2026). "Specifically, three genes were associated with increased asthma risk in the lung and a decreased risk for asthma in the blood (i.e., RERE, UNC13D, and OIP5-AS1), and two genes (i.e., RP5-1115A15.1 and DEF6) had the opposite effect." (PMID 39628479, 2024).
autoimmune lymphoproliferative syndrome (2 papers, 2013 to 2025). Autoimmune lymphoproliferative syndrome (ALPS) is a rare, inherited disorder characterized by non-malignant lymphoproliferation, multilineage cytopenias, and a lifelong increased risk of Hodgkin's and non-Hodgkin's lymphoma. "The loss of function variants (homozygous or heterozygous) of UNC13D is associated with susceptibility to autoimmune lymphoproliferative syndrome (ALPS)." (PMID 39992598, 2025).
Encephalopathy (2 papers, 2016 to 2025). Encephalopathy is a term that means brain disease, damage, or malfunction. "Neurological complications were common in patients with UNC13D deficiency, with all affected individuals presenting with convulsive seizures, which is consistent with previous reports that FHL3 patients often experience central nervous system involvement, including encephalopathy and seizures." (PMID 40901478, 2025).
juvenile idiopathic arthritis (2 papers, 2008 to 2024). Juvenile idiopathic arthritis (JIA) is the term used to describe a group of inflammatory articular disorders of unknown cause that begin before the age of 16 and last over 6 weeks. "In the last few years, an association has been observed between MAS in patients with juvenile idiopathic arthritis (JIA) and UNC13D mutations, particularly polymorphic variants in critical regulatory regions." (PMID 39469717, 2024).
pancreatic cancer (2 papers, 2022 to 2025). "For example, UNC13D is a calcium dependent cytoplasmic protein involved in vesicular and endocytic transport essential for vesicle maturation and docking and also known as an unfavourable prognostic marker in renal, endometrial and pancreatic cancer." (PMID 36582804, 2022).
airway hyperresponsiveness (1 paper, 2026). "oXER1 activates UNC13D‐dependent degranulation via calcium signaling, while UNC13D deficiency attenuates airway hyperresponsiveness." (PMID 41573111, 2026).
autoinflammatory syndrome (1 paper, 2025). A group of disorders of the innate immune system characterized by attacks of seemingly unprovoked inflammation without significant levels of either autoantibodies or autoreactive T cells more characteristic of autoimmune disease. "Furthermore, the co-occurrence of pathogenic variants in both DOCK11 and UNC13D in this patient underscores the potential complexity of genetic contributions to autoinflammatory syndromes and the value of comprehensive genetic evaluation in diagnostically challenging cases." (PMID 41250716, 2025).